SCAND2P (SCAN domain containing 2 pseudogene)
Synonyms: formerly SCAND2
Gene: Transcribed unprocessed pseudogene on chromosome 15 (84,631,963 to 84,642,066, forward strand). Ensembl gene ENSG00000176700.
Subcellular location: Nucleus
Diseases named in the same sentence as SCAND2P in open-access papers:
SCAND2P is named in the same sentence as 17 diseases in open-access papers, as found by Europe PMC text mining. Sharing a sentence is not in itself a finding about the gene and the disease. The quoted sentences say what the papers report.
prostate carcinoma (1 paper, 2023). A carcinoma that arises from epithelial cells of the prostate gland. "We next examined whether the gene expression of SCAN-TFs (MZF1, SCAND1, and SCAND2(P)) was correlated with HSF1 or HSF4 gene expression in prostate cancer specimens derived from patients." (PMID 36982267, 2023).
SCAND2P also shares sentences with these, for which no sentence is quoted: acute myeloid leukemia (1 paper); cancer (1); cervical cancer (1); colon adenocarcinoma (1); head and neck cancer (1); head and neck squamous cell carcinoma (1); lung adenocarcinoma (1); pancreatic cancer (1); pancreatic ductal adenocarcinoma (1); prostate adenocarcinoma (1); rectum adenocarcinoma (1); sarcoma (1); skin cutaneous melanoma (1); testicular germ cell tumor (1); tumor (1); uterine carcinosarcoma (1).